XIAP (X-linked inhibitor of apoptosis)
Diseases named in the same sentence as XIAP in open-access papers (continued):
Sharing a sentence is not in itself a finding about the gene and the disease.
bladder cancer (36 papers, 2012 to 2025). "The combination of XIAP mRNA detection and voided urinary cytology achieved better specificity and sensitivity, demonstrating that XIAP was a non-invasive diagnostic biomarker in low-grade bladder cancer." (PMID 33138314, 2020). "This assay consistently showed that knockout of XIAP markedly inhibited invasion of bladder cancer cells in vitro." (PMID 40133252, 2025). "We constructed a model of XIAP knockout and knockdown and XIAP overexpression in UMUC3 and T24T cell lines to investigate the direct downstream target of XIAP in promotion of metastasis of bladder cancer cells." (PMID 40133252, 2025). "Overall, this study provides new insights into the mechanism via which XIAP regulates metastasis of bladder cancer, demonstrating in particular that XIAP acts as a novel E3 ligase for YTHDC1." (PMID 40133252, 2025). "Immunoprecipitation-mass spectrometry (IP-MS) and iTRAQ were performed to identify the direct targets of XIAP in bladder cancer and the mechanisms involved." (PMID 40133252, 2025). "We have published studies demonstrating that XIAP promotes metastasis of bladder cancer by regulating MMP-2 mRNA." (PMID 40133252, 2025). "This XIAP-YTHDC1-MMP-2 regulatory axis represents a potential therapeutic target for bladder cancer intervention." (PMID 40986143, 2025). "This study is the first to demonstrate that XIAP is involved in regulation of m6A modification, which should lead to new avenues of research in bladder cancer." (PMID 40133252, 2025). "Our findings indicate that the ubiquitin E3 ligase XIAP promotes metastasis of bladder cancer cells by degrading YTHDC1." (PMID 40133252, 2025). "We also examined the expression of YTHDC1 in bladder cancer cells with knockout, knockdown, and overexpression of XIAP by western blotting." (PMID 40133252, 2025). "Knockdown of XIAP can inhibit invasion of bladder cancer cells and formation of lung metastasis in vivo." (PMID 40133252, 2025). "The present review focuses on the IAP members cIAP1, cIAP2, XIAP, Survivin and Livin and their importance as potential therapeutic targets in bladder cancer." (PMID 36845731, 2023). "miR‐200c has been reported to be downregulated, and in turn increased the stability of XIAP mRNA in bladder cancer." (PMID 37154878, 2023). "Then, researchers confirmed that XIAP enhanced the nucleolin-mediated Rho-GDIβ mRNA stability to promote bladder cancer cell invasion of the lung." (PMID 35992856, 2022). "Gefitinib, the FDA-approved EGFR inhibitor, was reported to sensitize human bladder cancer cell lines to TRAIL therapy via inhibition of protein kinase B (Akt) and X-linked inhibitor of apoptosis protein (XIAP) cascades." (PMID 35804815, 2022). "In bladder cancer, it was noticed that the expression of miR-200 is transcriptionally repressed by XIAP, which in turn upregulates the level of EGFR, a target of miR-200." (PMID 33435156, 2021). "The results of cell viability assay and immunoblot analysis as well as histone-complexed DNA fragments detection data revealed that MSSV treatment decreased the expression of Bcl-2 and XIAP in bladder cancer cells." (PMID 33430488, 2021). "The present data demonstrate the involvement of both intrinsic and extrinsic caspase pathways of apoptosis, which were associated with PARP-1 cleavage, Bax, and Fas induction, and Bcl-2 and XIAP suppression in a MSSV-treated bladder cancer cells." (PMID 33430488, 2021). "Both the BIR and RING domains of XIAP can promote anchorage-independent growth and invasion of bladder cancer cells." (PMID 33138314, 2020). "Among them, miR-200a and miR-200c were reported to participate in XIAP cascades in bladder cancer cells." (PMID 33138314, 2020).
bladder cancer (continued). "For example, XIAP has high expression in bladder cancer tissues and it accelerates disease progression." (PMID 33097010, 2020). "The important role of the Smac/XIAP rheostat was demonstrated in pancreatic and bladder cancer by using small molecule inhibitors for XIAP as well as Smac mimetics, which both enhanced TRAIL sensitivity." (PMID 31083589, 2019). "We also found regorafenib significantly reduces tumor growth, NF‐κB activation, and protein levels of tumor progression‐associated proteins (MMP‐9, XIAP, VEGF, and Cyclin‐D1) in bladder cancer in vitro and in vivo." (PMID 30801954, 2019). "We demonstrate here that XIAP is a strong positive regulator of EGFR expression in human bladder cancers and that XIAP BIR domain plays an important role in the mediation of EGFR protein expression by promoting its protein translation." (PMID 28057023, 2017). "XIAP is aberrantly increased in a variety of human cancers, including acute leukemia, ovarian carcinoma, bladder cancer, clear cell renal cancer, and many other cancers." (PMID 28057023, 2017). "A short-hairpin RNA (shRNA) specifically targeting human XIAP was used to knockdown endogenous XIAP in two different bladder cancer cell lines, T24T and UMUC3." (PMID 28057023, 2017). "Human XIAP was knockdown with short-hairpin RNA in two different bladder cancer cell lines, T24T and UMUC3." (PMID 28057023, 2017). "This is the first demonstration that XIAP promotes the anchorage-independent growth of human bladder cancer cell via positive regulation of EGFR translation." (PMID 28057023, 2017). "Activation of the EGFR signal pathway reduces TNF-α-related apoptosis-inducing ligand-induced apoptosis through AKT- and XIAP-dependent mechanisms in EGFR-dependent human bladder cancer cells." (PMID 26160843, 2015). "Based on these findings, we classified the five IAP members into three groups (1, cIAP1-N+Survivin-N; 2, cIAP1-C+cIAP2+XIAP; and 3, Survivin-C+Livin) and analyzed their corresponding clinical and pathological parameters in bladder cancer." (PMID 23599779, 2013). "In the present study, we detected the overall expression trends for Survivin, cIAP1, cIAP2, XIAP and Livin in normal bladder tissues and bladder cancer tissues through western blot analysis." (PMID 23599779, 2013). "In the present study, we investigated the overall expression trends of the five tumor-related proteins, Survivin, cIAP1, cIAP2, XIAP and Livin, in normal bladder tissues and bladder cancer tissues." (PMID 23599779, 2013). "In this study, we investigated the overall expression trends of the five tumor-related proteins, Survivin, cIAP1, cIAP2, XIAP and Livin, in normal bladder tissues and bladder cancer tissues." (PMID 23599779, 2013). "Our previous report demonstrated that elevated expression of XIAP was found in high stage and high grade bladder cancers." (PMID 22218530, 2012). "Increasing evidence suggests that XIAP promotes metastasis of bladder cancer but the underlying mechanism is not very clear." (PMID 40133252, 2025). "We identified an XIAP/YTHDC1/MMP-2 pathway that promotes metastasis of bladder cancer." (PMID 40133252, 2025). "We then hypothesized that YTHDC1 may have an important role in regulation of XIAP during metastasis of bladder cancer." (PMID 40133252, 2025). "Identification of substrates for XIAP could help us to understand how XIAP is involved in the development of bladder cancer and help to develop targeted therapies." (PMID 40133252, 2025). "Besides the research on the anti-apoptotic function of XIAP, some scholars have found that XIAP affects the invasion and lung metastasis of bladder cancer by regulating ERKS." (PMID 35992856, 2022). "In addition, the knockdown of XIAP attenuates anchorage-independent cell growth, suggesting that the anchorage-independent growth of bladder cancer can be modulated by the XIAP/miR-200/EGFR/EMT axis (see Section 3.3.2 for EGFR/EMT relationship)." (PMID 33435156, 2021).
bladder cancer (continued). "The expression of XIAP decreased in both of the MSSV-treated bladder cancer cells." (PMID 33430488, 2021). "For example, XIAP could increase MMP2 level to facilitate the progression of bladder cancer; moreover, XIAP also promotes the migration of esophageal cancer cells by enhancing epithelial–mesenchymal transition." (PMID 34650909, 2021). "Also, other researcher demonstrated that XIAP silencing resulted in the decline of GDIB expression accompanied with reduced cell invasion in bladder cancer." (PMID 32537125, 2020). "XIAP has generally been thought to function in bladder cancer." (PMID 31811115, 2019). "In addition, inhibition of XIAP activity by Embelin in bladder cancer cells not only reduces cell viability but also affects cell invasion in vitro, suggesting an important role of XIAP in tumor formation and progression." (PMID 28057023, 2017). "Our most recent studies have also shown that XIAP expression is overexpressed in human bladder cancers, revealing a crucial association between XIAP and human bladder cancer development (Data not shown)." (PMID 27447744, 2016). "Furthermore, the ectopic overexpression of X-linked inhibitor of apoptosis protein (XIAP) promotes the degradation of YTHDC1, whereas genetic ablation of XIAP elevates YTHDC1 expression, thereby suppressing metastatic progression in bladder cancer." (PMID 40986143, 2025). "However, the molecular mechanism by which XIAP promotes metastasis of bladder cancer remains unclear." (PMID 40133252, 2025). "However, in a recent study from our laboratories, it was seen that there was over-expression of RhoGDIβ in most clinical human BC tissues ( as compared to in paired adjacent normal tissues) and it is as a key XIAP downstream effector mediating bladder cancer (BC) invasion in vitro and in vivo." (PMID 37635218, 2023). "Therefore, simultaneous knockdown of antiapoptotic BCL2, Bcl-xL, XIAP and survivin may represent a promising treatment option for bladder cancer." (PMID 22797576, 2012). "These experiments revealed that XIAP promotes ubiquitination of YTHDC1, positively regulating expression of the MMP-2 and promoting metastasis of bladder cancer." (PMID 40133252, 2025). "XIAP is upregulated in patients with bladder cancer and in mouse models of BBN-induced muscle-invasive bladder cancer and can promote metastasis of bladder cancer cells, as found in our previous research." (PMID 40133252, 2025). "Collectively, these findings demonstrate that XIAP is a critical regulator of YTHDC1 and pinpoint the XIAP/YTHDC1/MMP-2 axis as a promising target for the treatment of bladder cancer." (PMID 40133252, 2025). "Our functional studies have shown that XIAP upregulated expression of MMP-2 by downregulating YTHDC1 and promoting metastasis of bladder cancer cells." (PMID 40133252, 2025). "Ectopic overexpression of XIAP promoted degradation of YTHDC1, and knockout of XIAP upregulated YTHDC1, which inhibited metastasis of bladder cancer." (PMID 40133252, 2025). "In this study, we demonstrated that XIAP is also a ubiquitin E3 ligase of YTHDC1, accelerating the degradation of YTHDC1 and promoting metastasis of bladder cancer." (PMID 40133252, 2025). "The findings of our present study suggest that XIAP and YTHDC1 interact to regulate the stability of MMP-2 mRNA and promote metastasis of bladder cancer." (PMID 40133252, 2025). "In human bladder cancer cells, ISO has been shown to reduce the levels of the anti-apoptotic protein XIAP, leading to enhanced apoptosis." (PMID 40362444, 2025). "It was reported that human bladder cancer tissues highly express several members of IAP proteins, including Survivin, cIAP1, cIAP2, XIAP, and Livin, which is an indicator of poor prognosis of bladder cancer." (PMID 36119107, 2022). "Overexpression of XIAP and BCL2 inhibits the apoptosis of cancer cells, and XIAP also enhances human invasive bladder cancer cell proliferation." (PMID 36430344, 2022).
bladder cancer (continued). "In this report, we have identified the FL118 differential modulation of apoptosis and the expression of anti-apoptotic proteins (survivin, XIAP, Mcl-1) in FL118-sensitive versus FL118-insensitive bladder cancer cells." (PMID 33217967, 2020). "This is the first demonstration of XIAP BIR domains as a potent positive regulator of EGFR expression, which in turn promotes bladder cancer cell anchorage-independent growth." (PMID 28057023, 2017). "We found that bladder cancer cells with a mutant Kras is highly sensitive to FL118-induced cell growth inhibition and cell death induction through inhibiting the anti-cancer cell death and drug resistance factors (survivin, Mcl-1, XIAP)." (PMID 33217967, 2020). "Moreover, treatment with 9-ING-41 led to a decreased expression of antiapoptotic molecules, Bcl-2 and XIAP, resulted in an increased apoptosis as shown by PARP cleavage in bladder cancer cells." (PMID 31882719, 2019). "Since miR-200a binds to the 3′-UTR of EGFR mRNA and inhibits EGFR protein translation, the attenuation of miR-200a expression by BIR domain of XIAP results in the enhancement of EGFR protein translation and increases the anchorage-independent growth of the bladder cancer cells." (PMID 28057023, 2017). "To investigate the functional interplay between XIAP and EGFR, we first examined whether XIAP affected EGFR expression levels in human bladder cancer cells." (PMID 28057023, 2017). "In the current study, we found that XIAP BIR domain could regulate EGFR expression through downregulating miR-200a by targeting protein phosphatase 2 (PP2A)/c-Jun axis and further promoted the bladder cancer cell anchorage-independent growth." (PMID 28057023, 2017). "However, hnRNPK knockdown did not affect XIAP mRNA levels in bladder cancer cells (data not shown), suggesting that the mechanism of hnRNPK on apoptosis differs between cancers." (PMID 27862976, 2017).
X-linked lymphoproliferative disease (35 papers, 2010 to 2025). X-linked lymphoproliferative disease is a hereditary immunodeficiency characterized, in the majority of cases, by an inadequate immune response to infection with the Epstein-Barr virus (EBV). "Genetic testing identified a mutation in the XIAP gene, confirming a diagnosis of X-linked lymphoproliferative disease." (PMID 39834491, 2024). "XIAP is an endogenous inhibitor of cell death and inactivating mutations of XIAP are responsible for X-linked lymphoproliferative disease (XLP-2) and primary immunodeficiency, but the mechanism(s) behind these contradictory outcomes have been unclear." (PMID 37347786, 2023). "In 2006, mutations in XIAP were found in 12 individuals belonging to three different families affected by X-linked lymphoproliferative syndrome (XLP)." (PMID 35740456, 2022). "Loss of function (LOF) variants in XIAP are known to be causative for X-Linked lymphoproliferative syndrome 2 (XLP2, OMIM 300635)." (PMID 35743704, 2022). "Mutations in XIAP have been associated with X-linked lymphoproliferative syndrome 2 (XLP2, MIM: 300635)." (PMID 32081864, 2020). "Dosage of the X-linked gene XIAP affects NK cell function in patients with X-linked lymphoproliferative syndrome presenting with chronic inflammatory bowel disease, which underscores the importance of X-linked gene expression in NK cells." (PMID 30671059, 2018). "Multiple PCR primers were designed for 6 genes using Ion AmpliSeqTM Designer; the SH2D1A and XIAP genes were included for distinguishing X-linked lymphoproliferative syndrome (XLP), which has a strong resemblance to HLH." (PMID 29783935, 2018). "However, in humans, defective expression of XIAP, due to deleterious mutations, is found to cause X-linked lymphoproliferative syndrome (XLP) type 2." (PMID 35406442, 2022). "X-linked lymphoproliferative disease (XLP) was diagnosed in eight patients: four cases each of SH2D1A (XLP1) and XIAP (XLP2) variants." (PMID 41300767, 2025). "The X-linked lymphoproliferative diseases (XLP) caused by pathogenic variants of SH2D1A (XLP1) and XIAP (XLP2) can also present with HLH." (PMID 35601409, 2022). "While defects in the gene SH2D1A were initially detected in patients with X-linked lymphoproliferative disease, known as XLP1, mutations in XIAP result in XLP2." (PMID 26581487, 2015). "A definitive diagnosis of X-linked lymphoproliferative disease is with mutation analysis for the SH2D1A and XIAP genes mutation." (PMID 24385755, 2013). "Rarely, it can be seen as an X-linked recessive disorder in association with XIAP (X-linked inhibitor of apoptosis protein, formerly BIRC4) mutations and X-linked lymphoproliferative disease." (PMID 22657725, 2012). "X-linked lymphoproliferative syndrome (XLP) is typified by vulnerability to Epstein-Barr virus (EBV) infection, dysgammaglobulinemia, and lymphoma – mutations in SH2D1A and XIAP genes are implicated, affecting the immune cell functions including NK cell and T cell activities." (PMID 40621451, 2025). "Such genes are SH2DIA, associated with X-linked lymphoproliferative syndrome (XLP) 1; XIAP, associated with XLP2; RAB27A, associated with Griscelly syndrome type 2; LYST, associated with Chediak–Higashi syndrome; and AP3BI, associated with Hermansky-Pudlak syndrome." (PMID 38541872, 2024). "The 46,XY patient with the XIAP deletion had mild global developmental delay but no symptoms characteristic of X-linked lymphoproliferative syndrome 2 [XLP2] caused by XIAP deficiency." (PMID 35907265, 2023). "Similarly, the development of intracellular staining protocols to detect expression of SAP, XIAP, or DOCK8 expedites the rapid diagnosis of the X-linked lymphoproliferative diseases or an autosomal recessive form of hyper-IgE syndrome (HIES), respectively." (PMID 31552044, 2019).
X-linked lymphoproliferative disease (continued). "Disease-causing mutations in XIAP/BIRC4 were first described in 2006 in families with patients suffering from X-linked lymphoproliferative syndrome (XLP) with no mutations in the SH2D1A gene encoding SAP." (PMID 23818254, 2013). "X-linked lymphoproliferative disease (XLP) is either caused by loss of the SLAM-associated protein (SAP; XLP-1) or the X-linked inhibitor of apoptosis (XIAP; XLP-2)." (PMID 36270981, 2022). "Furthermore, X-linked lymphoproliferative diseases: XLP1 (caused by defects of SH2D1A (OMIM #300490), encoding SLAM-associated protein (SAP)) and XLP2 (caused by changes in XIAP, which encodes the X-linked inhibitor of apoptosis (OMIM #300079) also frequently develop HLH." (PMID 34677667, 2021). "Finally, several primary immunodeficiency syndromes, including X-linked lymphoproliferative disease (XLP) type I due to hemizygous mutation of SH2D1Agene, OMIM *300490), and type II due to mutation of BIRC4/XIAP gene (OMIM *300079) are associated with a high risk of developing HLH." (PMID 22970278, 2012). "For instance, NKT cells may be absent in patients with some forms of X-linked lymphoproliferative disease (XLP), which is caused by mutations in the SH2D1A or XIAP genes." (PMID 20529312, 2010).